BIRC5 (baculoviral IAP repeat containing 5)
Diseases named in the same sentence as BIRC5 in open-access papers (continued):
Sharing a sentence is not in itself a finding about the gene and the disease.
tumor (continued). "For clinical translations, we found IAPs were strong prognostic markers for patient survival and tumor stage, with BIRC5 being the most potent biomarker for patient survival in multiple tumor types." (PMID 31964418, 2020). "Tumor-bearing (P = 0.031) and deceased status (P = 0.003) are also related with BIRC5 high expression." (PMID 31093306, 2019). "Downstream genes activated by STAT3 have been associated with tumor proliferation and survival, including PIM1/PIM2, MYC, BIRC5 and BCL2L134–39." (PMID 30741931, 2019). "BIRC5, however, is expressed at higher levels in tumor tissues compared to adjacent normal tissues in 98% (56 out of 57) of LUAD and 98% (50 out of 51) of LUSC patients." (PMID 29416000, 2018). "We further demonstrate that both adipocyte-induced oxidative stress and HO-1 overexpression result in splicing of the X-box protein XBP1 and activation of survival pathways involving survivin (BIRC5) and Bcl-xl in tumor cells." (PMID 29311669, 2018). "To better evaluate this relationship, we stratified NSCLC patients from TCGA into two groups based on the ratio of miR-195 expression to BIRC5 expression in tumor tissues." (PMID 29416000, 2018). "A high ratio of miR-195 to BIRC5 in tumor tissues is significantly correlated with better overall survival and recurrence-free survival in LUAD, but not LUSC." (PMID 29416000, 2018). "For the first time, we demonstrated that miR-203 inhibited tumor metastasis by downregulating BIRC5 and attenuating the TGFβ pathway, BIRC5 is a direct target of miR-203." (PMID 30241553, 2018). "For instance, BHLHE40 was reported to activate transcription of pro-survival factors in tumor cells, including BIRC5 and DeltaNp63." (PMID 30285805, 2018). "Hsa-miR-542-3p acts as tumor suppressor by targeting survivin (BIRC5), the oncogene astrocyte-elevated gene-1 (MTDH), or angiopoietin-2 (ANGPT2) that plays a role in tumor angiogenesis." (PMID 29293623, 2018). "Subsequently, multi-marker RT-PCR analysis was used to detect tumor-associated transcripts, including KRT19, MUC1, EpCAM, CEACAM5, and BIRC5." (PMID 28626429, 2017). "In human tumor tissue, BIRC5 has several characteristics, including a high expression level, a close association with proliferative activities, high transfer capacity, and resistance to chemotherapy." (PMID 29190974, 2017). "The cell proliferation rate as indicated by the percentage of Ki-67-positive tumor cells was increased in the group implanted with cells containing the BIRC5 plasmid and decreased in the group implanted with cells containing the miR-138-5p lentiviral vector." (PMID 27978829, 2016). "They observed a significant relationship between younger patients and BIRC5 mRNA level in tumor samples." (PMID 27372966, 2016). "The expression level of BIRC5 was significantly higher in tumor tissues than in control ovarian samples (p = 0.015)." (PMID 27323861, 2016). "There was also a significant correlation between BIRC5 expression and tumor-node-metastasis (TNM) stage." (PMID 25970782, 2015). "Survivin (encoded by Birc5), a member of the inhibitor of apoptosis protein (IAP) family, plays a crucial role in regulating apoptosis and contributes to tumor progression." (PMID 26271039, 2015). "Taken together, these data suggest a potential role for cyclin B1 and BIRC5 in PTTG1-mediated tumour growth." (PMID 26445238, 2015). "In LTL-418 tumor xenograft BIRC5 expression was mostly nuclear with a mix of nuclei with high and low staining." (PMID 25248616, 2014). "This compound was identified in a cell-based promoter activity assay and was described to specifically abrogate survivin gene (BIRC5) expression, resulting in preclinical activity in several tumor models both in vitro and in vivo." (PMID 25296978, 2014).
tumor (continued). "A relatively large fraction (between 20% and 58%) of the ARACNE_BIRC5 network partners (n = 45) were found among the up-regulated genes of r2 and r3 tumour subgroups, which was also significant by GSEA (p < 0.001)." (PMID 23835063, 2013). "The Dual-shRNA that targeted both OCT4 and BIRC5 inhibited tumor growth with great efficiency for a long period of time." (PMID 23433354, 2013). "When OCT4 expression was down-regulated by OCT4-shRNA in tumor cells, BIRC5 expression was also suppressed accompanied by an increase in the percentage of apoptotic cells." (PMID 23433354, 2013). "BIRC5-targeted therapy has been proposed to sensitize tumours to treatment and inhibit growth." (PMID 40683913, 2025). "Furthermore, BIRC5 knockout led to cell cycle arrest, cytokinesis defects, and autophagy activation, highlighting its essential role in tumor maintenance." (PMID 40471223, 2025). "These tumor-promoting processes that facilitate GBM growth may be downregulated by BIRC5 inhibitors such as YM155." (PMID 40422257, 2025). "This could be explained by the overexpression of BIRC5, which plays a crucial role in evading apoptosis, potentially favoring the survival of early tumor cells." (PMID 40725442, 2025). "The overexpression of BIRC5 could contribute to tumor cell survival and resistance, thus favoring disease progression." (PMID 40725442, 2025). "Comprehensive analysis of tumor databases revealed that the mRNA expression level of BIRC5 was significantly higher in tumors compared to corresponding normal tissues in all relevant unpaired samples, including BLCA, BRCA, CESC, CHOL, COAD, and 18 other tumor types." (PMID 39703228, 2024). "For example, survivin, also known as the BIRC5 protein, is overexpressed in TNBC, associated with a high proliferative capacity of tumor cells, so targeting survivin/BIRC5 may be an option for patients with TNBC." (PMID 39456858, 2024). "Interestingly, half of the genes analyzed, namely, BIRC5, TOP2A, PLK1, and RRM2, were associated with lung-specific neoplasms." (PMID 39596028, 2024). "BIRC5 is an apoptosis‐suppressing gene, which plays a role in inhibiting apoptosis in tumours." (PMID 37340587, 2023). "Consequently, its marked upregulation correlates with tumor resistance to chemotherapy; hence, the BIRC5 gene is a promising target for anticancer interventions." (PMID 37687120, 2023). "Therefore, downregulation of BIRC5 can act as an inhibitor of tumour cell migration and invasion through the PI3K/Akt signaling pathway." (PMID 37193964, 2023). "Taken together, we speculate that tumor‐intrinsic expression of Birc5 may contribute to the infiltration of MDSCs in tumor immune microenvironment." (PMID 37326143, 2023). "Our research suggested that BIRC5 might also contribute to PCa progression by altering the immune microenvironment of tumor cells." (PMID 37077837, 2023). "Given that BIRC5 is an IAP, we posited that BIRC5 might attenuate cisplatin sensitivity by modulating tumor cell apoptosis." (PMID 38112021, 2023). "Our observations indicated that the depletion of BIRC5 substantially reduced the tumor volume." (PMID 38112021, 2023). "Scutellarin exerts an anti‐tumour effect by downregulating the BIRC5 gene." (PMID 37340587, 2023). "Notably, we observed distinct differences in tumor weight and volume among the control group, the BIRC5 knockdown group, and the group with BIRC5 knockdown combined with IGF2BP1 overexpression." (PMID 38112021, 2023).
tumor (continued). "Survivin (also called BIRC5), a strategic and fundamental protein molecule in cancer, mainly plays the role of anti‐apoptosis and is exceedingly apparent in its expression in all tumour cells including bladder cancer." (PMID 37620295, 2023). "To determine the mechanism underlying the anti-tumor effects of YM155, we examined epigenetic modifications in the BIRC5 promoter and found that histone H3 lysine 27 acetylation (H3K27Ac) was highly enriched on the promoter region of BIRC5." (PMID 38203388, 2023). "Furthermore, studies have demonstrated that the ubiquitination and deubiquitylation of the BIRC5 protein can be regulated through diverse mechanisms to modulate tumor progression." (PMID 37958642, 2023). "Finally, we performed in vitro and in vivo experiments that demonstrated both tumor-promoting and immunosuppressing roles of BIRC5 in LUAD." (PMID 36046648, 2022). "Furthermore, the present research demonstrated that BIRC5 silencing dramatically suppressed cell proliferation, migration and invasion, as well as tumor growth in vivo, in parallelly." (PMID 35461228, 2022). "Accumulating evidence shows that BIRC5 (also known as survivin) is closely related to tumor progression, tumor progression, tumor recurrence, chemotherapy resistance and poor prognosis, and high expression levels of BIRC5 predicted a poor outcome for ccRCC patients." (PMID 36159976, 2022). "Assessments of tumor weight revealed that ectopic BIRC5 markedly enhanced tumor growth." (PMID 36046648, 2022). "Therefore, the anti-tumor effects of peptide vaccines targeting MHCI (BIRC5 and EphA2) and MHCII (PADRE) peptides were investigated using a vaccine composed of long multi-epitope peptides in this GL261 mouse model." (PMID 36439089, 2022). "Since BIRC5 is primarily expressed in tumor tissue, it may increase angiogenesis, promote cell division, and inhibit apoptosis." (PMID 36358602, 2022). "The effect of BIRC5 on tumor growth was also verified in PC xenograft model mice." (PMID 35461228, 2022). "Furthermore, we will perform more in vivo and vitro experiments to explore the function and the potential molecular mechanisms of BIRC5 in tumor metastasis and tumor microenvironment regulation of LGG." (PMID 35309512, 2022). "Furthermore, BIRC5 expression was elevated in tumor tissues across 59 LUAD samples and matched normal samples (p = 3.3e-21)." (PMID 36046648, 2022). "Studies on Taiwanese BC patients showed that BIRC5 was found in circulating tumor cells in their blood, and the results demonstrated that the expression of BIRC5 was significantly correlated with the size of the tumor, the histologic grade, the presence of lymph node metastases, and the TNM stage." (PMID 36358602, 2022). "Whereas abnormal DNA methylation in promoter regions of oncogenes as well as in tumour suppressor genes can be observed in most cancers, both hypermethylation and hypomethylation in the promoter sequence of BIRC5 may correlate with survivin overexpression." (PMID 35884555, 2022). "Therefore, BIRC5 suppression reduces the growth of BC cells, suggesting that BIRC5 functions as a tumor driver." (PMID 36358602, 2022). "Here, BIRC5 was strongly correlated with higher tumor grade and differentiation." (PMID 35178302, 2022). "Studies reported that circulating BC cells expressing BIRC5 might be related to several clinical characteristics, including tumor size, nodal involvement, HER2 expression, ER/PR status, and clinical stages of the illness." (PMID 36358602, 2022). "However, the potential molecular mechanisms of BIRC5 in tumor metastasis need to be explored in further studies." (PMID 35309512, 2022). "Accumulating evidence have also shown that BIRC5 is strongly expressed in tumor cells and may be essential for cell proliferation, apoptosis, and chemotherapy resistance." (PMID 35132928, 2022).
tumor (continued). "Several studies demonstrated that miR-101-3p was downregulated in LUAD and could inhibit tumor cell proliferation and invasion by targeting BIRC5 in LUAD." (PMID 35646670, 2022). "Therefore, the design of peptides that target the BIRC5/XIAP interface is important in the context of activating anti-tumor mechanisms in cells." (PMID 35053254, 2022). "Moreover, normal samples derived from blood, prostate, testis, thyroid, and uterus also displayed significantly higher BIRC5 expression patterns than their tumor counterparts." (PMID 35331169, 2022). "Similar to our findings, the oncogenic role of BIRC5 has been unveiled in other tumor diseases." (PMID 35461228, 2022). "Notably, classical Wnt target genes Axin2 and Birc5 (also known as Survivin) were significantly up-regulated only in late-passage Apc+/−;Bmal1−/− organoids that grow as tumor spheroids." (PMID 35947664, 2022). "In addition, BIRC5 over-expression was observed both in A549 and H460 cells compared to non-tumor human lung fibroblast HFL-1." (PMID 34372869, 2021). "In addition, it is suggested that BIRC5 can be used as a universal tumor antigen and a unique target for tumor immunotherapy." (PMID 34616672, 2021). "This specific intrinsic link between BIRC5 and interacting genes may be crucial to their role in tumor progression." (PMID 33431968, 2021). "In addition, the response of CANX, BID, NAMPT, and BIRC5 with different expression levels to immune checkpoint inhibitors was predicted based on Tumor Immune Dysfunction and Exclusion (TIDE) algorithm." (PMID 34988121, 2021). "In conclusion, our study highlighted RFWD3 may function as a tumor promotor in CRC via E2F1 transcriptional regulation of BIRC5, which might be used as a future therapeutic target for the more effective treatment of CRC." (PMID 34712656, 2021). "This study lays the foundation for future research on how BIRC5 modulates tumor immune cells, which may lead to the development of more effective targeted tumor immunotherapies." (PMID 33431968, 2021). "In KIRC, STAD, and UCEC, BIRC5 expression was higher in advanced tumor stages." (PMID 33431968, 2021). "According to the available data, it can be assumed that the BIRC5 gene may be a factor involved in tumor formation and the processes of disease invasion and progression." (PMID 33673050, 2021). "However, the use of NPs simultaneously loaded with AS-ODN and siBIRC5 down-regulated BIRC5 mRNA levels by 60% and 58% in A549 and H460 tumor cells, respectively." (PMID 34372869, 2021). "This suggests an immunomodulatory role for BIRC5 in tumor immunity." (PMID 33431968, 2021). "Moreover, our results showed that ACTG1, CSNK1D, PPP1CC, and BIRC5 expression was negatively correlated with miR-497-5p expression in HCC tumor biopsies (n = 364, r = −0.32, -0.29, -0.24, and -0.33, respectively, p < 0.001)." (PMID 33816607, 2021). "High expression levels of BIRC5 was observed in tumor-adjacent immune cells." (PMID 34804966, 2021). "Our research suggests that BIRC5 may be responsible for the condition of stem cell pluripotency, and its high expression may also be responsible for the dedifferentiation of tumor cells." (PMID 30774747, 2019). "Additionally, BIRC5 promotes the migration and invasion of tumor cells mediated by the TGF-β pathway and the PI3K/AKT pathway, interacts with proteins associated with DNA damage repair, and regulates tumor cell proliferation mediated via the β-catenin pathway." (PMID 31093306, 2019). "In addition, STAT3 is associated with tumor cell apoptosis through the regulation of BCL2, BAX, MCL1 and survivin (BIRC5)." (PMID 31287013, 2019). "It has been shown that BIRC5 was upregulated in tumor tissues." (PMID 31093306, 2019). "In addition, analysis of the GEO dataset (GSE31159) form 13 MM patients’ BM samples revealed that co-culture of MM primary tumor cells with BMSCs tended to increase BIRC5 mRNA relative to MM cells cultured alone in 10 out of 13 patients." (PMID 31638931, 2019).
tumor (continued). "HCC and non-tumor tissues exerted statistical difference in BIRC5 protein expression (P < 0.001)." (PMID 29707114, 2018). "After integrating the TCGA data and these datasets by using Standardized Mean Difference (SMD), we found that the BIRC5 expression level was significantly increased in the tumor group (SMD = 1.52, 95% CI: 1.23–1.83, P < 0.001) when using the random-effects model." (PMID 29707114, 2018). "Supporting a tumour suppressive role, SPDEF re-expression in SPDEF-negative OC cells inhibited cell proliferation and induced apoptosis, which was associated with reduced expression and promoter activity of the pro-survival gene, survivin (BIRC5)." (PMID 30200227, 2018). "MP-HX downregulated the expression of genes that could promote anti-apoptotic effect, cell cycle progression, tumor development and progression, which include BIRC5, CCNA2, CCNB1, CCNB2, CCNE2, CDK1/2/6, GINS2, HELLS, MCM2/10 PLK1, RRM2 and SKP2." (PMID 30042885, 2018). "Notably, promoter hypomethylation of BIRC5 (the gene that encodes surviving) is frequently found in OSCC, and leads to a more aggressive and invasive tumor phenotype." (PMID 28704968, 2017). "Of the total 40 tumor samples, 17.5% (7 cases) showed BIRC5 amplification." (PMID 27372966, 2016). "Furthermore, the biological consequences of the targeting of BIRC5 by miR-138-5p were examined in vitro via cell proliferation and invasion assays and in vivo using a mouse xenograft tumor model." (PMID 27978829, 2016). "Although BIRC5 is mainly involved in cell survival, reportedly, it may provide a beneficial source to fuel tumor cell-invasion and metastasis." (PMID 27821810, 2016). "Furthermore, BIRC5 expression level was found to be correlated with tumor-node-metastasis (TNM) grade in GBC patients." (PMID 25970782, 2015). "We hypothesize that miR-375 exerts its tumor suppressive role partly by acting as an upstream regulator of BIRC5 and BCL2L1 through the targeting of YAP1." (PMID 24892549, 2014). "Moreover, the comparison of survivin relative expression in different staged tumors (pT1, pT3, and pT4) revealed a much higher amount of BIRC5 transcripts in tumor tissues of pT3/pT4." (PMID 24945990, 2014). "Survivin mRNA was overexpressed in pediatric MPNST and associated to a copy number gain of BIRC5; furthermore, increased levels of transcripts correlated with a higher FNCLCC tumor grade (grade 1 and 2 vs. 3, p = 0.0067), and with a lower survival probability (Log-rank test, p = 0.0038)." (PMID 24303016, 2013). "A single-cell study of ibrutinib-treated MCL patients also found transcriptionally heterogeneous subpopulations within the same resistant tumor, which gained chr17q amplifications and resulted in elevating BIRC5 expression, which may lead to tumor cell proliferation." (PMID 40876452, 2025). "Thus, BIRC5 is highly correlated with aggressive tumor features." (PMID 38515208, 2024). "Our findings suggested that high levels of CDKN2A, BIRC5, and SPP1 were associated with poor overall survival in patients with HCC, suggesting that BIRC5, CDKN2A, and SPP1 are associated with HCC progression and could be used as tumor biomarkers in patients with HCC." (PMID 39042294, 2024). "However, since this result is based on bioinformatics, whether BIRC5 is also involved in PCa progression by affecting the tumor microenvironment still needs to be verified experimentally." (PMID 37077837, 2023). "Although BIRC5 is closely associated with tumor development, it is not tumor-specific." (PMID 36860953, 2023). "Gene expression analysis showed that chemokines such as Ccl2 and Ccl8 and cell proliferation markers such as Mki67 and Birc5 were highly expressed in cluster 3, indicating that 8 mg/kg of smTRAIL may induce tumor cell “activation” and secretion of chemokines to recruit immune cells." (PMID 37605148, 2023).